SMPD3 (sphingomyelin phosphodiesterase 3)
Diseases named in the same sentence as SMPD3 in open-access papers (continued):
Sharing a sentence is not in itself a finding about the gene and the disease.
ZIKV infection (4 papers, 2018 to 2022). "We assume that increased activation and levels of SMPD3, in neuronal cells perhaps is associated with the increased release of exosomes upon ZIKV infection." (PMID 30866785, 2019). "In a primary culture of murine neurons, an increase in exosome production was observed following ZIKV infection through the expression of neutral sphingomyelinase (nSMase)-2 or SMPD3, which regulate the production and release of exosomes." (PMID 32117303, 2020). "Our immediate future avenues will focus on this novel aspect to address the importance of SMPD3 and other neutral Sphingomyelinases in ZIKV infection and neuropathogenesis." (PMID 30866785, 2019). "SMPD3 silencing reduced the viral load, showing the important role for exosomes in ZIKV infection." (PMID 32117303, 2020). "Also, our work suggests that neutral Sphingomyelinase SMPD3 (also referred as nSMase2), an enzyme sphingomyelin phosphodiesterase is involved in ZIKV infection, replication, and mediates infectious viral RNA and protein transmission via neuronal exosomes." (PMID 30866785, 2019). "Given the importance of SMPD3 in mediating transmission of ZIKV through neuronal exosomes and GW4869 in inhibiting the viral loads in both neuronal cells and exosomes, we propose both as possible therapeutic candidates for controlling ZIKV infection and transmission in developing brains." (PMID 30866785, 2019).
asthma (3 papers, 2021 to 2025). "Interestingly, SMPD3 expression was prominently and specifically increased in severe COPD and not modulated in the (smaller) asthma cohort." (PMID 40553562, 2025).
Cognitive impairment (3 papers, 2018 to 2024). Abnormal cognition is characterized by deficits in thinking, reasoning, or remembering. "For example, Sphingomyelin Phosphodiesterase 3 (SMPD3) deficiency causes progressive cognitive impairment." (PMID 34182925, 2021).
psoriasis (3 papers, 2023 to 2025). An autoimmune condition characterized by red, well-delineated plaques with silvery scales that are usually on the extensor surfaces and scalp. "Some studies indicate that CD274 (PD-L1), CXCL13, BIRC5, and SMPD3 are important in the pathogenesis of psoriasis." (PMID 40557155, 2025). "In our study, we found that SMPD3 is closely related to the pathogenesis of psoriasis, indicating its importance in cellular signal transduction and lipid metabolism regulation." (PMID 40557155, 2025). "The ROC curves demonstrated that the expression levels of eight Hub Genes—POSTN, CD274, CD24, SERPINB3, CXCL13, SMPD3, BIRC5, and RAB27A—exhibited high accuracy (AUC > 0.9) in classifying the Psoriasis and Control groups." (PMID 40557155, 2025). "CD274 (PD-L1), CXCL13, BIRC5, and SMPD3 play the following roles in the IL-17a and IL-23 pathways: CD274 (PD-L1): The IL-17a and IL-23 pathways are closely related to the pathogenesis of autoimmune diseases like psoriasis." (PMID 40557155, 2025).
cholestasis (2 papers, 2019 to 2025). Impairment of the bile flow caused by obstruction within the liver, or outside the liver in the bile duct system. "Additionally, LCA-induced intrahepatic cholestasis showed elevated levels of ceramides (Cer) in mouse livers and hepatic expression of Smpd3, which were indicated as key factors that accelerated cholestasis." (PMID 30967781, 2019). "We found that enzymes contributing to CER production were upregulated by cholestasis, including DEGS2 in humans and Smpd3 and Cers3 in mice, indicating activation of CER generation by cholestasis." (PMID 40025008, 2025).
chondrodysplasia (2 papers, 2013 to 2024). "SMPD3 deficiency is the pathogenetic basis of a novel form of chondrodysplasia." (PMID 39136509, 2024).
chronic kidney disease (2 papers, 2018 to 2019). Impairment of the renal function secondary to chronic kidney damage persisting for three or more months. "Additionally, in vivo identification of CD63 with calcification of vessels of chronic kidney disease (CKD) patients implicates that SMPD3 is a potential novel therapeutic target to inhibit EV genesis and thus vascular calcification." (PMID 29682509, 2018).
dysplasia (2 papers, 2017 to 2020). A usually neoplastic transformation of the cell, associated with altered architectural tissue patterns. "SMPD3 was detectable in only one of the oral dysplasia/cancer cell lines by qRT-PCR, a finding that is consistent with our knowledge of SMPD3 expression in oral tumors." (PMID 28146434, 2017).
head and neck cancer (2 papers, 2019 to 2020). A primary or metastatic malignant neoplasm affecting the head and neck. "Although mutations in SMPD3 affect ~5% of acute myeloid leukemia and acute lymphocytic leukemia patients, mutations were found in only 1/279 (0.4%) tumors in the TCGA head and neck cancer dataset, with copy number variations present in only 3/279 (1%)." (PMID 32082486, 2020). "Among the cross-species downregulated genes, there are two additional genes that particularly noteworthy: SERPINB13 is an angiogenesis inhibitor that is downregulated in head and neck cancers, and the neutral sphingomyelinase SMPD3 is a cell cycle regulator." (PMID 30947707, 2019).
head and neck squamous cell carcinoma (2 papers, 2020 to 2022). A squamous cell carcinoma that arises from any of the following anatomic sites: lip and oral cavity, nasal cavity, paranasal sinuses, pharynx, larynx, and salivary glands. "In head and neck squamous cell carcinoma, the expression of cl8-Cer is significantly reduced; in addition, Cer metabolism-related enzymes, such as neutral SM hydrolase 2 (nSMase2 or SMPD3), can increase the level of Cer by hydrolyzing SM to inhibit cell proliferation and prolong cell cycle." (PMID 35782075, 2022).
Hyperglycemia (2 papers, 2021 to 2023). An increased concentration of glucose in the blood. "We found that hyperglycemia-induced SMPD3 activation increases sEV release, which could be counteracted by GW4869 treatment." (PMID 34951654, 2021). "Taken together, these findings in tissue-specific cells show that hyperglycemia converges on major insulin, lipid, and fibrosis pathways by DNA methylation to regulate the expression of core genes that consist of but are unlikely to be limited to MTOR, RPTOR, IRS2, TXNRD1, LCAT, SMPD3, and COL1A2." (PMID 36633903, 2023).
liver cancer (2 papers, 2018 to 2023). An epithelial or non-epithelial malignant neoplasm that arises from the liver. "Exosomal miR-27a-3p derived from mesenchymal stem cells inhibited the proliferation and metastasis of liver cancer cells, and its exosome target SMPD3 was identified." (PMID 37569824, 2023). "High serum exosomal miR-215-5p showed low disease-free survival in liver cancer patients, and its exosome targets SDC1 and SMPD3 were identified." (PMID 37569824, 2023).
microcephaly (2 papers, 2019 to 2024). A congenital or acquired developmental disorder in which the circumference of the head is smaller than normal for the person's age and sex. "Our immediate future research efforts will address the underlying molecular mechanisms of SMPD3 and other neutral Sphingomyelinases in mediating the transmission of ZIKV and its detrimental effects in causing microcephaly in neonatal brains." (PMID 30866785, 2019). "Our long-term future avenues will also delineate the schemes that depend on neutral Sphingomyelinases including SMPD3, that lead to enhanced cortical neuronal death, and the underlying molecular mechanisms for ZIKV-caused microcephaly in developing/neonatal brains." (PMID 30866785, 2019). "Taken together, our results suggest that ZIKV modulates SMPD3 activity in cortical neurons for its infection and transmission through exosomes perhaps leading to severe neuronal death that may result in neurological manifestations such as microcephaly in the developing embryonic brains." (PMID 30866785, 2019). "We hypothesized that the lack of microcephaly in the Smpd4 forebrain conditional KO mice could be due to Smpd3 compensatory sphingomyelinase activity in the mouse forebrain." (PMID 39470011, 2024).
muscular dystrophy (2 papers, 2020 to 2022). Muscular dystrophy (MD) refers to a group of more than 30 genetic diseases characterized by progressive weakness and degeneration of the skeletal muscles that control movement. "Next, to analyze whether loss of the nSMase2/Smpd3 gene in the mdx background affects muscular dystrophy via muscle-abundant miRNAs, we quantified the levels of the myomiRs miR-1, miR-133a, and miR-206 in the GAS muscles of mdx and mdx:Smpd3−/− (#11 and #238) mice." (PMID 33208172, 2020). "It has been shown that the inhibition of nSMase2/Smpd3 enzymatic activity ameliorates skeletal muscles of muscular dystrophy in mdx mice, in turn, inhibits ceramide synthesis." (PMID 35163475, 2022). "However, the involvement of nSMase2/Smpd3 in muscular dystrophy and the abnormal behavior observed in DMD patients has not yet been elucidated." (PMID 33208172, 2020).
schizophrenia (2 papers, 2025 to 2026). A major psychotic disorder characterized by abnormalities in the perception or expression of reality. "Our results showed a selective association of SMPD3 polymorphisms with a schizophrenia diagnosis and of SMPD1 expression in the PFC." (PMID 39825014, 2025). "An initial analysis of human gene polymorphisms and brain gene expression in schizophrenia patients identified an association of SMPD1 and SMPD3 genes coding for ASM and NSM." (PMID 39825014, 2025). "Here, an analysis of human gene polymorphisms and brain gene expression in schizophrenia patients identified an association of SMPD1 and SMPD3 genes coding for acid- (ASM) and neutral sphingomyelinase-2 (NSM)." (PMID 39825014, 2025). "Among the four analyzed sphingolipid-genes, we identified three SNPs in SMPD3, coding for neutral sphingomyelinase-2 (NSM), that showed significant association with schizophrenia." (PMID 39825014, 2025).
tauopathies (2 papers, 2019 to 2021). "Similarly, a deficiency of Smpd3 encoding nSMase2, as detected in the KIN nervous tissue, was reported to cause TDP-43 neurotoxicity and tauopathy, while ataxin-2 depletion protects against TDP-43 aggregation and tauopathies." (PMID 31766565, 2019).
alcohol abuse (1 paper, 2021). The use of alcoholic beverages to excess, either on individual occasions ("binge drinking") or as a regular practice. "We identified spontaneous genetic variations in the SMPD3 gene, which are related to alcohol abuse, affective behaviour, and bone mineralisation in humans." (PMID 34584229, 2021).
astrocytoma (1 paper, 2020). "Interestingly, the astrocytoma cell line available to us (BT142) presented higher expression of SMPD3 and ASAH2 compared with the oligodendroglioma." (PMID 33050528, 2020). "Overall, certain sphingolipid genes (e.g., SMPD3 and ASAH2) follow a similar pattern; their mRNA levels are very high in oligodendroglioma, followed by astrocytoma, and finally the lowest in glioblastomas." (PMID 33050528, 2020). "Indeed, a comparison of SMPD3 and ASAH2 proteins levels in these cell lines show an upregulation of the sphingolipid degradation pathway in both oligodendroglioma as well as astrocytoma." (PMID 33050528, 2020).
atopic dermatitis (1 paper, 2023). "On the other hand, using a non-invasive transcriptomic analysis of surface lipids, Shima and colleagues (2022) observed a lower expression of SMPD3 in children with mild-to-moderate atopic dermatitis compared with healthy children." (PMID 36837912, 2023).
COVID-19 (1 paper, 2023). A disease caused by infection with severe acute respiratory syndrome coronavirus 2. "The expression levels of Cer-metabolizing enzymes derived from SM, such as sphingomyelinases (SMPD2 and SMPD3), were found to be downregulated in COVID-19 severity." (PMID 37566018, 2023).
fibrosis (1 paper, 2024). the formation of excess fibrous connective tissue in an organ or tissue in a reparative or reactive process. "Strong associations existed between methylation of CpG units within Smpd3 and traits in adipose and liver of NASH and mild fibrosis explored." (PMID 37588221, 2024). "Additionally, average methylation of Smpd3 was significantly higher in the liver than in adipose tissue in both NASH and mild fibrosis mice, and mRNA expression of Smpd3 was significantly lower in the liver than in adipose tissue." (PMID 37588221, 2024).
metabolic syndrome (1 paper, 2023). A cluster of metabolic risk factors for CARDIOVASCULAR DISEASES and TYPE 2 DIABETES MELLITUS. "Since excess ceramide production causes lipotoxicity, metabolic dysregulation and atherogenesis, dual targeting of both DES1 and Smpd3/nSMase2 may be a novel strategy for treatment of metabolic syndrome and importantly deadly co-morbidities." (PMID 36894641, 2023). "However, targeting both DES1 and Smpd3 may be a novel, more potent therapeutic approach for the treatment of metabolic syndrome." (PMID 36894641, 2023).
oral cancer (1 paper, 2020). "Since nutrient stress is common in tumors, we investigated whether SMPD3 plays a similar role in oral cancer cell lines by comparing the survival of control and SMPD3-overexpressing lines after 48 hours in serum-free media." (PMID 32082486, 2020).
pancreatic cancer (1 paper, 2020). "Thus, the coordinated regulation of ANXA1 and sphingomyelin phosphodiesterase 3 (SMPD3) may promote exosome biogenesis in pancreatic cancer." (PMID 32756339, 2020). "In pancreatic cancer, the treatment of cancer cells and CAFs with GW4869, a SMPD3 inhibitor, interrupts exosome secretion, resulting in the impediment of angiogenesis and survival of cancer cells." (PMID 32756339, 2020).
periodontitis (1 paper, 2024). An acute or chronic inflammatory process that affects the tissues that surround and support the teeth. "Among the AgP-related suggestive genes, we selected the genes which have been reported to be associated with periodontitis and are expressed in the periodontal tissue, and found two genes, sphingomyelin phosphodiesterase 3 (SMPD3) and paraoxonase-1 (PON-1)." (PMID 39917667, 2024). "Besides PON-1 and SMPD3, there have been no reports directly showing the association between the identified genes and periodontitis." (PMID 39917667, 2024).
tricho‐rhino‐phalangeal syndrome (1 paper, 2023). "Mutations in the Trps1 gene lead to the human condition tricho‐rhino‐phalangeal syndrome which is characterised by craniofacial and skeletal dysplasias and siRNA mediated knockdown of Trps1 in a pre‐odontoblastic cell line leads to the suppression of Phospho1, Alpl and Smpd3 expression." (PMID 36540015, 2023).
tumor (49 papers, 2013 to 2026). "The enzymatic activity of SMPD3 results in the hydrolysis of sphingomyelin to produce ceramide, a bioactive lipid that has been implicated in tumor suppression and cellular stress responses." (PMID 40226357, 2025). "Ceramide, the bioactive product of SMPD3, plays a pivotal role in regulating cellular stress responses and has been implicated in tumor suppression." (PMID 40226357, 2025). "As one of the tumor suppressors linked to preventing cell proliferation and promoting tumors, SMPD3, also known as nSMase2, works as an enzyme to convert sphingomyelin into ceramide and phosphorylcholine." (PMID 37588221, 2024). "The gene encoding SM phosphodiesterase 3 (SMPD3), also referred to as neutral sphingomyelinase 2 (nSMase2), which is predominantly localized at the cytosolic leaflet of the plasma membrane, and responsible for surface membrane SM hydrolysis was identified as a tumor suppressor gene in primary HCC." (PMID 37367067, 2023). "By regulating key processes such as apoptosis, cell proliferation, stress responses, autophagy, and the tumor microenvironment, SMPD3 emerges as a significant tumor suppressor." (PMID 40226357, 2025). "The prognostic impact of SMPD3 expression was assessed in HCC patients based on different tumor stages (T1, T2, and T3)." (PMID 40226357, 2025). "The cohort was divided into groups based on low and high levels of SMPD3 expression in tumor tissues, according to the median IHC score." (PMID 40226357, 2025). "The TNM stage of the tumor also showed a significant correlation with SMPD3 expression levels (p = 0.016)." (PMID 40226357, 2025). "We assessed tumor-related phenotypes in SMPD3-overexpression and control cells, including proliferation, migration, and invasion capacities." (PMID 40226357, 2025). "Taken together, the mechanistic insights into SMPD3's role in HCC highlight its multifaceted impact on tumor biology." (PMID 40226357, 2025). "A ≥2-fold decrease in SMPD3 expression in the tumor was observed in 16/27 (59%) of patients, whereas a ≥2-fold increase was observed in 3/27 (11%)." (PMID 32082486, 2020). "We identified the promoter region of SMPD3 as a site of frequent hypermethylation in patient-derived oral tumors and further analyzed its function in oral dysplasia and tumor cell lines." (PMID 32082486, 2020). "Neurofilament, heavy polypeptide (NEFH) and sphingomyelin phosphodiesterase 3 (SMPD3) were also defined as tumor suppressor genes that were hypermethylated and silenced in HCC." (PMID 33299889, 2020). "However, a significant relationship was observed between SMPD3 expression and tumor size (p < 0.001)." (PMID 40226357, 2025). "Elucidating the interactions between SMPD3 and these pathways could provide insights into how SMPD3 influences tumor progression and patient outcomes." (PMID 40226357, 2025). "SMPD3 and ceramide also influence the tumor microenvironment." (PMID 40226357, 2025). "Interestingly, we found that patients with extracapsular spread exhibited significantly lower SMPD3 expression in the tumor (Student’s t-test, t = 2.254, p = 0.025)." (PMID 32082486, 2020). "In addition, we found that SMPD3 methylation correlates with tumor grade and lymphovascular invasion." (PMID 32082486, 2020). "Interestingly, it was also found that reconstituting SMPD3 in mouse tumor cells that did not express this gene led to increased cell death, suggesting that normal SMPD3 counteracts pro-proliferative phenotypes associated with AML cells." (PMID 36361536, 2022). "Moreover, SMPD3 downregulation promotes tumor progression in oral squamous cell carcinoma (OSCC)." (PMID 35565311, 2022). "In detail, patients were stratified based on several variables, including age, sex, HBV infection status, AFP level, tumor size, pathological grade, differentiation, resection margin, portal vein invasion, TNM stage, and SMPD3 expression level." (PMID 40226357, 2025).